PPARG (peroxisome proliferator activated receptor gamma)
Diseases named in the same sentence as PPARG in open-access papers (continued):
Sharing a sentence is not in itself a finding about the gene and the disease.
colitis (continued). "In reality, the preventative and therapeutic efficacy oftargeting PPARγ with thiazolidinediones for treatmentof colitis is debatable." (PMID 18615192, 2008). "The bases of the protective action of PPARγ in colitis are reduced proinflammatory cytokine production, attenuated expression of ICAM-1 and COX-2, inhibition of NF-κB and JNK/p38 MAPK, and modification of immune cell activity." (PMID 19125181, 2008). "Collectively, knockoutanimals have confirmed a potential protective role of PPARγ in colitis but additional research isstill required to understand fully how tissue specific PPARγ expression influences differentmanifestations of colonic inflammation." (PMID 18615192, 2008). "In various animal models of IBD, the activation of PPARα or PPARγ has anti-inflammatory effects in the intestine, resulting in decreased production of inflammatory markers and slower progression of colitis." (PMID 19125181, 2008). "Perhaps the strongest evidence for ananti-inflammatory role of PPARγ comes from landmark studies indicatingthat heterozygous PPARγ deficient mice were more susceptible toDSS- and TNBS-induced colitis." (PMID 18615192, 2008). "The PPARγ, MAPK, and NF-κB signaling pathways are closely associated with colitis." (PMID 40076616, 2025). "Transcriptome data from colitis patients (GSE59071) were used to observe PPARγ gene expression." (PMID 40948937, 2025). "Furthermore, our study confirms the therapeutic effect of IBN on mouse colitis and further demonstrates its ability to activate the PPARγ signaling pathway and inhibit pyroptosis in IECs." (PMID 40948937, 2025). "Similarly, Moringa oleifera leaf polysaccharide ameliorates DSS-induced colitis by enhancing PPARγ and decreasing TLR/MyD88/NF-κB signaling pathway." (PMID 38699583, 2024). "A small amount of evidence has demonstrated I3C, an AhR ligand found in diet, is capable of modulating PPARγ expression in colitis models in vivo and that thiazolidinedione derivates can, in turn, activate AhR, but these findings are products of serendipity rather than the result of focused studies." (PMID 39684781, 2024). "Concerning genes with anti-inflammatory effects, significantly increased levels of IL-10 (3.8 ± 2.0 vs. 0.9 ± 0.3, p < 0.05) and PPARγ (0.8 ± 0.0 vs. 0.6 ± 0.0, p < 0.05) mRNA were observed in the colon of rats with colitis treated with the synbiotic compared to untreated animals." (PMID 39409061, 2024). "Similarly to the effect of exogenous treatment with inosine, BL protects against DSS-induced colitis by improving adenosine 2A receptor/PPARγ-dependent mucosal barrier functions." (PMID 39062500, 2024). "Similarly, B. pseudolongum supplementation was also found to be able to attenuate colitis by increasing the intestinal proportion of Foxp3+T cells and modulating the Pparγ/STAT3 pathway in DSS-fed mice." (PMID 39275234, 2024). "In response to DSS, colons of TLR4-SNP mice produced reduced levels of M2a Mφ marker mRNA and protein, including PPARγ, and therapeutic administration of the PPARγ agonist ligand, rosiglitazone, resolved colitis in TLR4-SNP mice, and increased expression of the M2a protein, Ym1." (PMID 37768050, 2023). "Furthermore, Muc2 secretion in DSS-induced mouse colitis is positively regulated by the peroxisome proliferator-activated receptor-gamma (PPAR-γ) via the PPAR-γ/long myosin light chain kinase (MLCK)-dependent pathway." (PMID 37371485, 2023). "Novel PPARγ activators are also being investigated for the treatment of colitis in animals." (PMID 37242462, 2023). "Therefore, Pygo2 knockdown in Il‐10−/− mice can promote PPARγ expression and induce the differentiation of adipocytes, while also inhibiting mesenteric fat inflammation, thereby inhibiting colitis." (PMID 35707871, 2022). "Bp7 and Bp8 intervention elevated the expression of STAT3 and PPARγ in colitis mice." (PMID 35681301, 2022).
colitis (continued). "Additionally, the studies in both LPS-stimulated RAW 264.7 cells and the colonic tissues of DSS-induced colitis mice indicated that COS can upregulate the level of peroxisome proliferator-activated receptor gamma (PPARγ)." (PMID 35743209, 2022). "Future work testing whether targeted disruption of intestinal epithelial cell PPARγ abolishes ghrelin’s therapeutic effect in attenuating DSS-induced colitis in vivo is required to confirm this observation." (PMID 36614012, 2022). "Importantly, their time-series transcriptional characterization of colitis identified epithelial cell function and PPARγ signaling among the key pathways downregulated during the acute (days 6–10) and recovery phases (days 12–14) of DSS-induced inflammation." (PMID 36614012, 2022). "However, Bp7 and Bp8 intervention drastically down-regulated the expression of Tlr4, NF-κB, iNOS, and COX2 and drastically up-regulated the expression of STAT3, Nrf2, and PPARγ in colitis mice (p < 0.05)." (PMID 35681301, 2022). "Together, our data show that ghrelin alleviated DSS-induced colitis, suggesting that ghrelin may promote tissue repair in part through regulating epithelial metabolism via PPARγ mediated signaling." (PMID 36614012, 2022). "Furthermore, exogenous treatment of inosine reproduced similar protective effects as BL to protect against DSS-induced colitis through improving adenosine 2A receptor (A2AR)/PPARγ-dependent mucosal barrier functions." (PMID 33820558, 2021). "Experimental colitis can be relieved by increasing PPARγ expression through PPARγ agonists." (PMID 34769138, 2021). "Furthermore, the sesquiterpene β-caryophyllene (BCP) can reduce DSS-induced colitis in mice with a mechanism associated with CB2 and PPARγ, which leads to the inhibition of pro-inflammatory cytokines and NF-κB." (PMID 33498177, 2021). "The results showed that the two PPARγ agonists significantly reduced the levels of 2-HG and H3K4me3 in colons of mice with colitis, regulated the levels of GSH and ROS in lymphocytes of colonic lamina propria, and the effects were weakened by GLS1 overexpression." (PMID 33754076, 2021). "Moreover, we identified for the first time that inosine, a gut microbial purine metabolite, contributed to the protective effects of BL against DSS-induced colitis by improving A2AR/PPARγ-dependent mucosal barrier functions." (PMID 33820558, 2021). "However, PPARγ signaling inhibition by GW9662 abolished the protective effects of BL on DSS-induced colitis." (PMID 33820558, 2021). "PPARG is expressed at high levels in the colon, and the role of this nuclear receptor in controlling inflammation has been well documented in several animal models of colitis and in patients with UC51." (PMID 34075172, 2021). "Innate immune cells are also affected by dietary fat as activation of peroxisome proliferator-activated receptor gamma (PPARγ) by conjugated linoleic acid protected mice from DSS induced colitis and the deletion of PPARγ in macrophages aggravated dextran sulfate sodium (DSS)-induced colitis." (PMID 33801480, 2021). "Interestingly, many natural ligands that present in food such as conjugated linoleic acid have been reported to efficiently prevent the development of colitis through PPARγ signaling activation." (PMID 33820558, 2021). "Satisfactory anti-inflammatory effects of PPARγ in colitis models has been well investigated." (PMID 33380244, 2021). "Butyrate protects mice against colitis and increases the PPARγ expression levels in vivo." (PMID 34691046, 2021). "Similarly, consumption of milk SM effectively decreased disease activity and colonic inflammatory lesions in mice with chemically induced colitis, partly through PPARγ." (PMID 32260440, 2020). "Because the PPARγ system is a relevant target for the treatment of inflammatory diseases and pain, molecular mechanisms underlying the healing of intestinal mucosal injury and analgesic effect of pioglitazone in DSS-induced colitis mice were clarified here." (PMID 31989391, 2020).
colitis (continued). "Moreover, the relationship of murine Lcn2 and peroxisome proliferator-activated receptor gamma (PPARγ) in colitis models and lipid studies reveals a relevant intracellular pathway of aberrant Lcn2 expression regulated by PPARγ." (PMID 32188494, 2020). "TZDs, such as pioglitazone, troglitazone, and rosiglitazone, also provide protection in mouse models of colitis or colon cancer cell lines, suggesting that colonic PPARγ may be a potential therapeutic approach against UC in humans." (PMID 32536865, 2020). "Peroxisome proliferator-activated receptor gamma (PPARγ), a number of the nuclear hormone receptor family, exerts a crucial role in mediating inflammatory diseases (e. g., colitis, liver steatosis, and rheumatoid arthritis) and inflammatory and neuropathic pain development." (PMID 31989391, 2020). "Pharmacological activation of PPARγ in a T cell-transfer colitis model resulted in increased colonic Tregs and decreased Th17 cells in the gut mucosa, whereas deletion of PPARγ in CD4+ T cells impaired mucosal Tregs and enhanced colitogenic Th17 responses in mice with CD4+ T cell-induced colitis." (PMID 32403220, 2020). "Furthermore, administration of rosiglitazone, a synthetic PPARγ agonist, attenuated the colonic damage by increasing the expression of epithelial barrier protein following induction of murine colitis with DSS." (PMID 32775340, 2020). "One classic anti-inflammatory drug, namely 5-ASAs, augments PPARγ expression and promotes its translocation from the cytoplasm to the nucleus resulting in activation of peroxisome-proliferator hormone response element-driven genes to suppress colitis activity." (PMID 31139192, 2019). "Administration of a PPARγ agonist attenuated the experimental colitis." (PMID 29494512, 2018). "Depletion of PPARγ in mouse CEC increases susceptibility to experimental colitis, while activation of this receptor reduces intestinal inflammation and disease severity both in experimental models of colitis and in UC patients." (PMID 28928735, 2017). "In summary, bergenin could ameliorate colitis in mice through inhibiting the activation of macrophages via regulating PPARγ/SIRT1/NF-κB-p65 pathway." (PMID 29375382, 2017). "Colonic PPARγ expression is linked to host–microbe interactions with natural (e.g., SCFA—butyrate, conjugated LA) and synthetic (e.g., 5-aminosalicylic acid) PPARγ ligands preventing inflammation in experimental colitis." (PMID 28804483, 2017). "PPARγ also forms heterodimers with RXRα, and anti-inflammatory effects and amelioration of experimental colitis has been described with a number of PPARγ agonists through trans-repression of signal-dependent transcription factors that mediate inflammatory programs of gene activation." (PMID 28223944, 2017). "Thus, the TNBS-induced colitis associated intestinal fibrosis in rats was performed, and the related parameters such as E-cadherin, α-SMA, and PPARγ were evaluated, as well as the DAI and CDMI scores in colon." (PMID 28203261, 2017). "However, it was suggested that PPARγ is required for the development of colitis in a lymphopenic environment due to the increased apoptosis of PPARγ-deficient T cells." (PMID 27548145, 2016). "Studies in animals have demonstrated that S. salivarius significantly inhibited inflammation in TNBS-induced colitis mouse models suggesting that the PPARγ-independent inhibition of NF-κB counterbalances the inhibition of PPARγ transcriptional activity observed in our study." (PMID 25946041, 2015). "Another study found that during colitis PPARγ RNA levels are decreased in the intestinal lamina propria and peritoneal exudate and that adenoviral gene transfer of PPARγ rescued sensitivity to PPARγ ligands and reduced markers of inflammation and improved mouse survival." (PMID 26713087, 2015).
colitis (continued). "The role of PPARγ in the etiology and treatment of colitis has been of great interest, because its ligands have long been used to treat type-2 diabetes and are known to decrease the severity of colitis induced in mouse models." (PMID 24465207, 2014). "Furthermore, the observation that intestinal epithelium-specific ablation of PPARγ aggravates dextran sodium sulfate (DSS)-induced colitis demonstrates the strong influence of intestine-derived PPARγ on colitis severity." (PMID 24465207, 2014). "Gene expression analysis revealed down-regulation of PPARγ after colitis induction." (PMID 23382912, 2013). "After an extensive search of medical literature in English language from the PubMed database, we aim in this paper to focus on potential role of PPARγ in the predisposition and physiopathology of IBD and to analyze its role in experimental colitis and potential therapy for IBD." (PMID 22997506, 2012). "Preventive administration of thiazolidinediones did in fact provide beneficial effects in murine models of ulcerative colitis but was less efficient when administered after the onset of the disease because PPARγ was shown to be downregulated by colitis-induced inflammatory processes." (PMID 21949655, 2011). "Indeed, PPARγ levels have been shown to bedownregulated in epithelial cells and macrophages during colitis." (PMID 18615192, 2008). "It remains unclear what phase, if any, would be bestfor targeting PPARγ with thiazolidinediones for treatmentof colitis: during the initiation, low grade, moderate, high grade, orremission phases of colitis." (PMID 18615192, 2008). "Recentstudies have revealed 2, 4, 6-trinitrobenzene sulfonic acid-induced colitis to besignificantly reduced after the administration of both PPARγ and RXR agonists, and this beneficial effect is reflected by thereduction in the NF-κB DNA binding activity in the colon." (PMID 18528526, 2008). "With the exception of one contradictory study showing that long-term pretreatment with a PPARγ agonist aggravated colitis, the preventive activation of PPARγ was efficient, whereas the efficacy of ligand administration after the onset of the disease was dependent on the levels of PPARγ." (PMID 19125181, 2008). "Furthermore,we demonstrated ligands for PPARγ and PPARα inhibit colitis-related coloncarcinogenesis usingour AOM/DSS mouse model." (PMID 18483618, 2008). "Additionally, expression validation through the MAPK and PPARγ signaling pathways suggests that CUM may also inhibit the MAPK and PPARγ signaling pathways to alleviate colitis in mice." (PMID 40076616, 2025). "Moreover, it has been described that the pharmacological effects of BCP may involve PPARγ in vascular inflammation, arthritis, and colitis models." (PMID 37891972, 2023). "Thus, we hypothesize that elevation of TDAG51 negatively regulates PPARγ activity or PPARγ expression per se in DSS-induced colitis model mice, thereby possibly promoting the production of inflammatory mediators via the TLR4/NF-κB signaling pathway." (PMID 36450854, 2022). "Thus, Bp7 and Bp8 ameliorate colitis by activating the PPARγ/STAT3 pathway." (PMID 35681301, 2022). "Hence, PPARγ agonists can attenuate colitis in mouse models." (PMID 35431918, 2022). "However, whether COS can alleviate colitis by activating the PPARγ/SIRT1-mediated NF-κB signaling pathway is still unclear." (PMID 35200626, 2022). "Overall, our findings suggest that the gut microbiota-inosine-A2AR/PPARγ axis plays an important role in the maintenance of intestinal homeostasis, which may represent a novel approach for colitis prevention via manipulation of the gut microbial purine metabolite." (PMID 33820558, 2021). "Thus, our results suggest that the microbiota-inosine-A2AR/PPARγ axis could have tremendous potential for preventing and treating intestinal inflammatory disorders, such as colitis." (PMID 33820558, 2021).
colitis (continued). "Oral administration of the four components of C. asiatica could attenuate colitis in mice, but it’s mainly madecassoside acid, the active form of madecassoside, when topically administered in the colon, weakened colitis by regulating Th17/Treg balance via affecting the PPARγ/AMPK/ACC1 pathway." (PMID 33013406, 2020). "In addition, the same studies in OXA-induced colitis mice indicated that treatment with Tetramethylpyrazine could improve the outcome of intestinal inflammation via PPARγ signaling-mediated inhibition of NF-kB signaling." (PMID 32536865, 2020). "This study demonstrated that systematic administration of pioglitazone, an agonist of PPARγ, could alleviate DSS-induced colitis, attenuate colitis-associated mechanical hyperalgesia, and improve integrity of the intestinal mucosal barrier by directly upregulating tight junction proteins." (PMID 31989391, 2020). "Thus, PPARγ expression in IECs and lamina propria mononuclear cells is protective against colitis." (PMID 30804707, 2019). "Studies in human subjects have revealed that colonic epithelial cells from ulcerative colitis patients display drastically reduced expression of PPARγ, suggesting that its presence in gut epithelium may have a protective effect against colonic inflammation in humans." (PMID 24465207, 2014). "Therefore, the loss of PPARγ in Treg impairs their ability to control effector CD4+ T-cell responses preventing protection against colitis in a mouse model of intestinal inflammation suggesting that expression of PPARγ by Treg is required for optimal anti-inflammatory efficacy." (PMID 23983678, 2013). "However, in the past few years there has been a flurry of research investigating the role of CLA isomers in experimental colitis because PPARγ is abundantly expressed in this tissue, and it appears that the protective effects of CLA isomers are due to the activation of PPARγ." (PMID 22792089, 2012). "Based on the evidence that (a) thiazolidinedionescan suppress inflammatory gene expression in vitro and (b) PPARγ expression protects against the developmentof colitis in several animal models, it seems logical that PPARγ might be a good target for treatment ofgut inflammation." (PMID 18615192, 2008). "Moreover, Katayamaet al. showed that the lack of therapeutic responsiveness to thiazolidinedionesduring colitis could be restored by adenoviral-mediated reexpression of PPARγ in the colon." (PMID 18615192, 2008). "Therefore, we hypothesize that IBN produced by the metabolism of valine by P. goldsteinii plays a role in resisting colitis by activating the PPARγ signaling pathway, reducing the expression of TJs in IECs, and affecting the integrity of the intestinal epithelial barrier." (PMID 40948937, 2025). "The authors also showed that the polysaccharide-modulated key signaling pathways, including the NF-κB, MAPK, and PPARγ signaling pathways, inhibited the NLRP3 inflammasome signaling pathway, resulting in a reduction in DSS-induced colitis inflammation." (PMID 40283898, 2025). "Nitrated oleic acid activates PPARγ, reduces colonic inflammation, and improves symptoms of DSS-induced colitis." (PMID 37868958, 2023). "Both in vitro and in vivo, the colitis increased NF-kB and NF-kB-p65, COX-2, iNOS, IL-1β, IL-6, and TNF-α activity, in addition to decreasing PPARγ expression." (PMID 36677021, 2023). "We extended our findings in the IL-4Rα−/− mice by showing that mice in which PPARγ had been deleted in myeloid cells (133, 147, –, 149) were also extremely sensitive to DSS-induced colitis." (PMID 37768050, 2023). "Interestingly, in these models, the protective effects of thiazolidinediones may be primarily mediated via hematopoietic cells because conditional PPARγ deletion in the intestinal epithelium causes mild spontaneous colitis and increased susceptibility to DSS-induced colitis." (PMID 37554552, 2023).